RNU6-610P (RNA, U6 small nuclear 610, pseudogene)
Gene: Small nuclear RNA gene on chromosome 15 (43,637,632 to 43,637,738, reverse strand). Ensembl gene ENSG00000206991.
Homologues: Orthologues: chimpanzee U6 (98% identical), guinea pig U6 (81% identical), rabbit U6 (79% identical), mouse Gm55901 (77% identical). Paralogues in human: RNU6-354P (100% identical), RNU6-45P (92% identical), RNU6-12P (91% identical), RNU6-13P (91% identical), RNU6-21P (91% identical), RNU6-26P (91% identical), RNU6-31P (91% identical), RNU6-32P (91% identical), RNU6-949P (91% identical), RNU6-1 (90% identical), RNU6-15P (90% identical), RNU6-17P (90% identical), and 1286 more.